SERPINH1 (serpin family H member 1)
Diseases named in the same sentence as SERPINH1 in open-access papers (continued):
Sharing a sentence is not in itself a finding about the gene and the disease.
tumor (continued). "Notably, SERPINH1 gene was one of the validated targets of miR‐30c‐2‐3p, again indicating its oncogenic function in agreement with the tumor‐suppressive role of miR‐30c‐2‐3p." (PMID 30913346, 2019). "SERPINH1 may play an important role in tumor metastasis because of promoting maturation of various types of procollagens." (PMID 29921304, 2018). "Furthermore, localizing CAF-like astrocytes via SERPINH1/COL5A1 expression may help better delineate tumor extent during GBM diagnosis and treatment." (PMID 40530702, 2025). "CESC patients with high SERPINH1 expression exhibited widespread suppression of lipid metabolism, yet selectively activated the unsaturated fatty acid synthesis pathway, which may be an adaptation to the metabolic demands of tumor metastasis." (PMID 40705756, 2025). "Unlike the prevailing research has examined the molecular function of SERPINH1 within epithelial cancer cells, our study provides compelling evidence that SERPINH1—a frequently overexpressed ECM protein in tumor tissues—may be localized to stromal cell (i.e., fibroblasts) rather than cancer cells." (PMID 39305996, 2024). "High expression of SERPINH1 may contribute to tumor immune-suppressive status." (PMID 36105106, 2022). "Moreover, SERPINH1 played an important role in tumor microenvironment and immune regulation." (PMID 36105106, 2022). "It suggested that SERPINH1 may become a potential tumor marker." (PMID 36105106, 2022). "In addition, research had proved that knocking down SERPINH1 could observably inhibit the invasion, migration, and proliferation of tumor cells." (PMID 36105106, 2022). "To conclude, SERPINH1 may play a important role as a prognostic biomarker for human pan-cancer and the results of this study may provide a novel and effective immunological antitumor strategy for tumor immunity research." (PMID 35058967, 2021). "In the HPA database, the protein expression of SERPINH1 and COL5A1 was higher in tumor tissues than in normal tissues." (PMID 40530702, 2025). "SERPINH1 enhances ECM integrity by supporting proper collagen folding, facilitating tumor cell survival." (PMID 40959429, 2025). "In breast cancer, esophageal squamous cell carcinoma, and gastric cancer, elevated SERPINH1 levels promote collagen deposition and remodeling of the tumor microenvironment (TME), enhancing tumor cell invasion and metastasis." (PMID 40705756, 2025). "Differentially expressed genes such as FAP, SERPINH1, and the newly reported PSAPL1 are involved in tumor progression, extracellular matrix remodeling, and immune response modulation." (PMID 41244835, 2025). "In vivo, SERPINH1 and HAPLN1 were validated to tumor-enriched and NAT-enriched proteins, each with IHC." (PMID 39305996, 2024). "In TCGA, significant differences were observed in the expression levels of SERPINH1 and GPR37 between normal tissues and LUAD tumor tissues." (PMID 39052154, 2024). "qPCR experiments also demonstrated markedly upregulated expression of SERPINH1 and GPR37 in tumor tissues." (PMID 39052154, 2024). "Therefore, targeting SERPINH1 may be more lethal to tumor cells." (PMID 36105106, 2022). "In our analysis, high expressions of SERPINH1 and P3H1 were found to correlate positively with immune infiltration and immune checkpoints in the tumor microenvironment." (PMID 34880916, 2021). "SERPINH1 and P3H1 both correlated negatively with tumor purity and positively with CD8+ T cells, B cells, macrophages/monocytes, dendritic cells (DC), cancer associated fibroblasts (CAF), endothelial cells, neutrophils, and natural killer (NK) cells." (PMID 34880916, 2021). "We also analyzed HSPH1, HSPD1, SERPINH1, HSPA4, and HSP90AA1 expression as a function of the HNSC tumor stage." (PMID 32523426, 2020). "In summary, our results indicate that HSPH1, HSPD1, SERPINH1, HSPA4, and HSP90AA1 are significantly upregulated in HNSC patients and their upregulation is negatively correlated with HNSC tumor stage." (PMID 32523426, 2020).
tumor (continued). "Furthermore, reported in various cancers except for EAC as relevant to activating PI3K-Akt signaling pathway or promoting tumor through SENP3/SP1/SQLE axis, SERPINH1 was also identified as a key gene in EAC in the current study." (PMID 40872572, 2025). "As a result, the distribution of CAF-like astrocytes—marked by SERPINH1 and COL5A1—could help more precisely define tumor boundaries during diagnosis and treatment." (PMID 40530702, 2025). "Notably, genes such as FAP, SERPINH1, and PSAPL1 have emerged as promising biomarker candidates due to their significant upregulation in GC tissues and their functional relevance in tumor progression, extracellular matrix remodeling, and immune evasion." (PMID 41244835, 2025). "We propose that changes in the expression of SERPINH1 and COL5A1 may induce astrocytes to adopt CAF-like characteristics, potentially promoting tumor invasiveness and metastasis." (PMID 40530702, 2025). "A deeper investigation into the interaction mechanisms between SERPINH1, PLOD1, ITGA5, and ESM1, and how they collectively influence tumor biological behavior, may reveal potential therapeutic targets for novel treatment strategies." (PMID 40705756, 2025). "We also observed a downregulation of stress response proteins (HSPA1A/HSPA1B, HSPA5, SERPINH1), suggesting that TSA might affect cellular stress response pathways, potentially impacting tumor cell survival." (PMID 40429900, 2025). "The dramatic increase in the stromal levels of SERPINH1/heat shock protein 47, that was discovered using our ECM proteomic pipeline, was validated by immunohistochemistry (IHC) of “Tumor” and “Matched Normal” tissues, obtained from an independent cohort of LSCC patients." (PMID 36228107, 2023). "PTK7, SERPINH1, and FAP could discriminate PanIN versus tumor‐related stroma by contrast to αSMA and LRRC15." (PMID 36587397, 2023). "Considering that the up-regulation of SERPINH1 expression level was related to shorter OS, DSS and PFI, we speculated that SERPINH1 may involved in tumor immune response." (PMID 35058967, 2021). "Due to the spontaneous and diffuse tumorigenesis of the DEN-CCI4 murine model, our sampling was limited and we were unable to accurately distinguish between tumor and non-tumor tissues, resulting in the inability to separately describe the effects of targeting SERPINH1 on tumor and NAT tissues." (PMID 39430252, 2024). "The tumor center was characterized by a higher abundance of transferrin (TF), endoplasmic reticulum oxidoreductase 1 (ERO1)-like protein (ERO1A), EH domain-containing protein 1 (EHD1), keratin 5 (KRT5), serpin H1 protein (SERPINH1), and lactate dehydrogenase A (LDHA)." (PMID 35512017, 2022). "Therefore, SERPINH1 might influence the infiltration of CD8+ T cells and M2 macrophages by affecting the tumor microenvironment–related immune pathways to promote tumor development." (PMID 36105106, 2022). "Indeed, several of the identified genes in our study are reported to be involved in angiogenesis, tumor angiogenesis and arteriogenesis, i.e. IL-8, ET-1, CARP, HPTPη, ID1, MGSA, SMAD7, HO-1, RHOB, PTHLH, SERPINH1/HSP47, JAG1, GNA13 and TEAD4." (PMID 16594992, 2006).
cancer (75 papers, 2009 to 2025). A tumor composed of atypical neoplastic, often pleomorphic cells that invade other tissues. "The previous studies have indicated a close association between SERPINH1 and cancer development, as it can facilitate cancer growth and invasion by modulating the extracellular matrix." (PMID 39052154, 2024). "Abnormal expression of SERPINH1 is considered a prognostic marker for cancer, and it is associated with immunoregulators and immune infiltration." (PMID 38306098, 2024). "The correlation analysis of 46 immune-stimulating genes demonstrated that SERPINH1 expression was highly associated with CD276 in most cancers." (PMID 36105106, 2022). "The results of the infiltration level demonstrated that SERPINH1 was negatively correlated with CD8+ T cells but positively associated with M2 macrophages through different algorithms in pan-cancer." (PMID 36105106, 2022). "SERPINH1 plays a key role for the correct folding and secretion of different types of collagen and has previously been associated to cancer progression." (PMID 35027621, 2022). "The Kaplan–Meier analysis of OS, DSS, and PFI also represented that SERPINH1 is a risk factor for patients in many kinds of cancer." (PMID 36105106, 2022). "We utilized the TIMER database to explore potential associations between SERPINH1 and the infiltrating immune cells across human cancers." (PMID 35058967, 2021). "Taken together, our results suggest that SERPINH1 affects the prognosis of patients and is associated with immune infiltration in many cancers, especially in brain lower grade glioma (LGG)." (PMID 35058967, 2021). "SERPINH1 is associated with ulcerative colitis-associated carcinomas, local lymph node metastasis, chemotherapy resistance, and poor prognosis in CRC." (PMID 34880916, 2021). "HSP47 is encoded by the SERPINH1 gene, which is located on chromosome 11q13.5, one of the most frequently amplified regions in human cancer." (PMID 32928242, 2020). "It is encoded by the SERPINH1 gene located on chromosome 11q13.5; this region is one of the most frequently amplified in human cancer." (PMID 32928242, 2020). "That means SERPINH1 may play a risk factor in most human cancers." (PMID 36105106, 2022). "However, the mutations and mutation sites of SERPINH1 in cancer are rarely reported." (PMID 35058967, 2021). "SERPINH1 was initially identified as an endoplasmic reticulum retention protein, and recent studies have established a connection between aberrant SERPINH1 expression and tumorigenesis in malignant tumors." (PMID 40771930, 2025). "In this study, we developed a novel CAF-related prognostic model using data from the The Cancer Genome Atlas and Gene Expression Omnibus databases and identified SERPINH1 and COL5A1 as CAF-related genes in GBM." (PMID 40530702, 2025). "The SERPINH1 (HSP47 gene) is located on chromosome 11q13, a region usually amplified in human cancers." (PMID 39135385, 2024). "The results of its OS, DSS, and PFI analyses further confirmed that SERPINH1 is a worse factor in various cancers." (PMID 36105106, 2022). "The mRNA and protein expression levels of SERPINH1 have been reported to be significantly upregulated in GC tissues compared with normal tissues, and inhibition of SERPINH1 significantly suppressed cancer cell migration and invasive abilities." (PMID 36104825, 2022). "In this research, the prognostic significance of SERPINH1 for pan-cancer was evaluated using the Kaplan–Meier analysis and univariate Cox regression analysis." (PMID 36105106, 2022). "We also carried out gene expression, gene changes, survival status, immune infiltration, and functional enrichment analysis to investigate the potential molecular mechanisms of SERPINH1 in the pathogenesis or clinical prognosis of different cancers." (PMID 36105106, 2022). "For the analysis of 24 immune-inhibiting genes, we found that SERPINH1 expression was highly associated with CD276, TGFBI, VEGFA, HAVCR2, IL10, and ADORA2A in most cancers." (PMID 36105106, 2022).
cancer (continued). "The GTEx database was used to further explore the mRNA expression of SERPINH1 in pan-cancer of TCGA." (PMID 36105106, 2022). "To further explore the connection between SERPINH1 and the infiltration of various immune cells in pan-cancer, we analyzed the 22 immune cells by using the CIBERSORT method." (PMID 36105106, 2022). "We found that SERPINH1 overexpressed in later stages in most cancers, including ACC, BLCA, KIRC, LIHC, and KIRP (all p < 0.05)." (PMID 36105106, 2022). "First, the exact significance of SERPINH1 expression in various cancers and the exact implication of immunoregulation in these cancers remain incomplete." (PMID 36105106, 2022). "A pan-cancer analysis reported that SERPINH1 strongly correlated with worse survival in various cancers." (PMID 36110953, 2022). "We further found the co-expression of SERPINH1 with immune checkpoint markers across cancers, specifically in TGCT (38/47), LGG (35/47), and PRAD (32/47)." (PMID 35058967, 2021). "In summary, this study revealed that SERPINH1 was highly expressed and related to poor prognosis in a variety of cancers, especially in BLCA, COAD, HNSC, KIRC, KIRP, and LIHC." (PMID 35058967, 2021). "The high expression of SERPINH1 significantly reduced the overall survival (OS), disease-specific survival, and progression free interval in eleven cancers." (PMID 35058967, 2021). "The genetic alteration status of SERPINH1 in different cancer samples were observed via the TCGA cohorts." (PMID 35058967, 2021). "Furtherly, we evaluated the relationship between the expression of SERPINH1 and the prognosis of pan-cancer patients." (PMID 35058967, 2021). "In a very recent study, SERPINH1 was shown to induce cancer cell-platelet interaction through type I collagen and promote cancer metastasis." (PMID 34194496, 2021). "An in-depth exploration of the mechanism by which SERPINH1 promotes cancer development is also warranted." (PMID 34194496, 2021). "In this study, we observed the genetic alteration status of SERPINH1 in different cancers and evaluated the correlation of SERPINH1 expression with TMB and MSI." (PMID 35058967, 2021). "To explore the potential of SERPINH1 to promote cancer development, we analyzed the effect of SERPINH1 knockdown on SW480 cell apoptosis." (PMID 34194496, 2021). "In the present study, we systematically analyzed 33 types of cancer to investigate the correlation between SERPINH1 expression and the patients’ prognosis." (PMID 35058967, 2021). "Previous studies have shown the relationship between the overexpression of SERPINH1 and many kinds of cancers." (PMID 33860039, 2021). "SERPINH1, or heat shock protein 47, is required for the correct folding of various types of collagen and has already been connected to cancer progression." (PMID 33377644, 2020). "Abnormal expression levels of SERPINH1 are frequently found in a variety of cancers, including cervical, lung and gastric cancers." (PMID 32523426, 2020). "SERPINH1, a serpin peptidase inhibitor also named heat shock protein 47, has been reported to driver cancer cell invasion by regulating extracellular matrix gene network." (PMID 31722693, 2019). "The location of SERPINH1 is at chromosome 11q13.5, a domain frequently abnormal in various human cancers." (PMID 31249732, 2019). "The unique properties of SERPINH1 in modulating collagen production and its location on the cell membrane in many forms of cancer have led SERPINH1 to be designated as a potential biomarker or therapeutic target for a number of conditions and diseases." (PMID 29239102, 2018). "Recent studies have shown that silencing SERPINH1 by small molecules can suppress cancer cell phenotypes 36, 37 that lead to poor prognosis." (PMID 29239102, 2018). "Furthermore, SERPINH1 has been identified as a potential molecular marker and therapeutic target in various malignant tumors." (PMID 39052154, 2024). "SERPINH1 was a hazardous marker in most of the cancer types." (PMID 37091161, 2023).
cancer (continued). "SERPINH1 and BCART1 are associated with various immune checkpoint genes in some cancers." (PMID 36817484, 2023). "SERPINH1 was found to be a potential prognostic biomarker based on a pan-cancer analysis." (PMID 37091161, 2023). "So, we analyzed the SERPINH1 expression in pan-cancer to find out its value in immunotherapy." (PMID 36105106, 2022). "In addition, SERPINH1 also related to their receptors in pan-cancer, such as CXCR4, CCR1, and CCR10." (PMID 36105106, 2022). "The RNA expression of SERPINH1 in pan-cancer data was first evaluated using the Oncomine database." (PMID 36105106, 2022). "Infiltrating levels of cancer-associated fibroblasts (CAF) and macrophages were elevated in high SERPINH1 expression samples, whereas infiltrating levels of B cells, CD4+ T cells, and CD8+ T cells were downregulated in high SERPINH1 expression samples compared to low SERPINH1 expression samples." (PMID 36104825, 2022). "Studies have confirmed that SERPINH1 may promote cancer growth and invasion by regulating the extracellular matrix network." (PMID 36105106, 2022). "Therefore, SERPINH1 is likely to be a potential target in immunotherapy or become a prognosis biomarker in pan-cancer." (PMID 36105106, 2022). "Our research is the first pan-cancer analysis of SERPINH1 using the TCGA project and GTEx database." (PMID 36105106, 2022). "All this results infer that SERPINH1 may recruit and regulate infiltrating immune cells to inhibit or promote the progression of cancers, which strongly suggest that SERPINH1 serves as a key factor in cancer immunity." (PMID 35058967, 2021). "In this study, we aimed to analysis the expression of SERPINH1 across various cancer types." (PMID 35058967, 2021). "Consequently, the suppression of SERPINH1 by miR-29- overexpression canceled the progression of cancers." (PMID 35118144, 2021). "According to this analysis, we speculated that the favorable prognostic value of SERPINH1 is based on the key involvement of this protein in the A-C process (carcinogenesis) as well as the progression (local and distant metastasis) of cancer." (PMID 34194496, 2021). "The role of SERPINH1 in cancer is largely unexplored, and its functions appear to be inconsistent." (PMID 35058967, 2021). "In addition, SERPINH1 was correlated with multiple immunoregulators and immune infiltration level in a variety of cancers, particularly in BRCA, LGG, and LIHC." (PMID 35058967, 2021). "SERPINH1, and its dependent collagen secretion might promote cancer metastasis through cancer cell-platelet interactions." (PMID 34880916, 2021). "That means SERPINH1 may be significantly related to poor prognosis in pan-cancer." (PMID 36105106, 2022). "That means SERPINH1 might become a potential immunotherapy target in some carcinomas." (PMID 36105106, 2022). "However, the role of SERPINH1 in pan-cancer is largely unexplored." (PMID 35058967, 2021). "Thus it can be seen that SERPINH1 interacts with immune regulation and may become a potential biomarker which has an important impact on the development of cancers and prognosis of patients." (PMID 35058967, 2021). "This trend was further supported by TCGA pan-cancer data (STAD), revealing a significant upregulation in SERPINH1 gene expression in tumors compared to normal tissues (P = 1.4e − 13), even in early-stage cancer (stage I; P = 2.2e − 10)." (PMID 38907287, 2024). "For example, exploration of epigenetic mechanisms that regulate fibroblast activity in cancer point to the role of miR-29a and its direct effect on both LOXL2 and serpin peptidase inhibitor clade H, member 1 (SERPINH1)." (PMID 38873180, 2023). "Also, SERPINH1 may become a potential immunotherapy target in pan-cancer." (PMID 36105106, 2022). "The results showed that SERPINH1 was related to the immunostimulators, immunoinhibitors, MHC molecules, TILs, receptors, and chemokines in multiple types of human cancers." (PMID 35058967, 2021).